PVT1 (Pvt1 oncogene)
Diseases named in the same sentence as PVT1 in open-access papers (continued):
Sharing a sentence is not in itself a finding about the gene and the disease.
cancer (continued). "Therefore, further research is required to explore PVT1 as a bona fide target in cancer therapy based on lncRNAs." (PMID 36894542, 2023). "It has been widely reported that PVT1 promotes tumor growth in different types of cancer." (PMID 37573419, 2023). "Interestingly, our study also revealed hub genes (MEG3, MIAT, IRF1, ADAMTS9-AS2, TP63, NOD2, NOD1, NLRP3, MAGI2-AS3, and PVT1, respectively) within the pyroptosis-related ceRNA network, some of which have been well-studied in the field of cancer biology." (PMID 37511974, 2023). "Previous studies suggested that PVT1 could promote the occurrence and development of cancers by affecting cell proliferation, migration, invasion and apoptosis." (PMID 37202742, 2023). "It is reported that PVT1 is typically upregulated in many types of cancer samples." (PMID 35036445, 2022). "PVT1 is a potential predictor of cancer progression and patient prognosis." (PMID 35794862, 2022). "PVT1 is an emerging biomarker for the diagnosis and treatment of cancer." (PMID 36195846, 2022). "Evidence has dissected that lncRNA PVT1 could be chemotherapy and radiotherapy sensitizer in cancer." (PMID 36438563, 2022). "Treatment of the cell line with ketamine, an NMDA (N-methyl-D-aspartate) receptor antagonist widely used as analgesic for cancer pain treatment, decreases the p300-recruitment on PVT1 promoter, thus inhibiting the lncRNA repressing activity on CDKN1C expression." (PMID 35456025, 2022). "After screening by integrating the sequencing results and online database, LncRNA PVT1 were chosen for further study, not only because it has been shown to have important oncogenic features in several types of cancer, but also because it was reported to interact directly with STAT3 in cancer cells." (PMID 36266267, 2022). "ncRNAs such as PVT1 and its targeted transcription factors (TF) often form feedforward loop in cancer progression, as ncRNAs themselves may be downstream transcripts of TF." (PMID 36266267, 2022). "MYC was also found to co-amplify with PVT1 in several cancer cell lines." (PMID 36761693, 2022). "Saleembhasha and Mishra 32, first published in 2017 working with a TCGA RNA-seq dataset of 5601 samples from 15 different primary cancer types, proposed a pan-cancer regulatory axis consisting of PVT1, E2F1 and FOXM1 as common gene expression regulatory entity." (PMID 35534592, 2022). "The PVT1 gene has been widely investigated for its roles in cancer." (PMID 34754096, 2022). "PVT1 is a long non‐coding RNA (lncRNA) showing aberrant expression in multiple human cancer types." (PMID 35398964, 2022). "Notably, evidence for putative tumor‐suppressive elements in the PVT1 locus remains to be observed in human cancer, where PVT1 is typically upregulated compared to normal cells." (PMID 34668345, 2022). "According to reports, the biological activity of many cancer cells can be modulated by PVT1." (PMID 36295083, 2022). "Furthermore, PVT1 regulates several cancers processes and pathways such ad cell–cell adhesion and TGF‐β signaling pathway." (PMID 35027621, 2022). "Increased lncRNA PVT1 expression is required for MYC protein upregulation in human cancer cells." (PMID 36118202, 2022). "The ability of HPV integration to alter expression of nearby human genes (within 500 Kb) has been demonstrated in both OPSCC and UCSCC with recurrent integration sites identified near genes implicated in cancer such as MYC, MYB, PVT1, RAD51B, EMBP1, CD274/PD-L1, and SOX2." (PMID 36139648, 2022). "In addition, HCC patients with PVT1 rs3931282 AA + GA genotypes were less prone to develop late-stage cancers in a stratified analysis of clinical characteristics." (PMID 36418931, 2022). "PVT1 downregulation promotes the ferroptosis of live cancer cells." (PMID 36230902, 2022). "Further studies revealed that knockdown of PVT1 could sensitize cancer cells to GEM, while the overexpression of PVT1 blocked this effect in PC cells." (PMID 35565245, 2022).
cancer (continued). "Furthermore, knockdown of YTHDF2 in cancer cells was shown to attenuate the upregulation of PVT1 and reversed the half-life of PVT1, indicating that YTHDF2 was vital to the stability of PVT1 and affected the progression of tumors." (PMID 35382893, 2022). "Besides harboring MYC, dysregulation and amplification of which is found in many human cancers, the 8q24.21 locus also harbors lncRNA PVT1 53 kb downstream of MYC." (PMID 35820706, 2022). "This review describes the mechanisms of action of PVT1 in various cancers." (PMID 36195846, 2022). "Furthermore, its reliability in serum samples as a biomarker of cardiac damage and cancer makes PVT1 an attractive therapeutic target and a potential biomarker of SR." (PMID 35328496, 2022). "In addition, plasmacytoma variant translocation 1 (PVT1) is a kind of lncRNA located at 8q24.21, which has been proved to play a regulatory role in many cancers and may become a potential biomarker of clinical pathological characteristics of different types of cancers." (PMID 35399100, 2022). "Therefore, it is possible that a positive feedback mechanism exists between PVT1 and c-Myc, in which c-Myc promotes PVT1 expression and then PVT1 prevents the degradation of c-Myc, driving the expression of both oncogenes in cancer." (PMID 33499210, 2021). "have identified the cancer-promoting effect of lncRNA PVT1 initiated by binding to miR-195." (PMID 33869744, 2021). "Its application in five cancers (colon, liver, kidney, stomach, or thyroid; total samples n = 2024) identified various dysregulated key features (such as PVT1 expression and ABI3BP alternative splicing) and pathways (especially liver and kidney dysfunction) shared by multiple cancers." (PMID 34946814, 2021). "Moreover, human tissue and mouse xenotransplantation studies have indicated that the overall survival rate and tumor size of many cancer types are related to PVT1 overexpression." (PMID 34336125, 2021). "PVT1 functioned importantly in promoting cancer viability, autophagy and metastasis." (PMID 33391456, 2021). "Among all dysregulated lncRNAs in cancers, PVT1 is particularly compelling because emerging studies have revealed that PVT1 fulfills significant oncogenic effects in the onset and progression of various cancers, including ccRCC." (PMID 34321604, 2021). "PVT1 was shown to play an oncogenic role as an inducer of progression of certain human cancers." (PMID 33817293, 2021). "Indeed, many of PVT1 targets are also downstream signalling molecules of c-Myc, strengthening the idea that they both work together to drive cancer progression." (PMID 33499210, 2021). "Moreover, depletion of PVT1 resulted in decreased c-Myc expression and increased apoptosis of cancer cells." (PMID 34527584, 2021). "PVT1 is a crucial oncogenic lncRNA that is highly expressed in cancer cells." (PMID 34336125, 2021). "Lnc-PVT1 located at 8q24.21, is a novel biomarker for diagnosing cancer." (PMID 34947913, 2021). "The study of this regulatory pathway in which lncRNAs and microRNAs are involved might allow for the design of promising therapies to reduce the expression of lncRNA PVT1 or increase the levels of miR-17-3p to achieve cancer regression." (PMID 34439196, 2021). "Recent studies have revealed PVT1 to be an oncogenic marker for multiple cancer types." (PMID 34336125, 2021). "Recent studies indicated circular PVT1 also had an important role in cancer progression, whose roles in OV remain unclear." (PMID 33391456, 2021). "Additionally, our study gave prominence to the prognostic value of common and cancer-specific differently expressed lncRNAs in cancer outcomes, such as PVT1." (PMID 34335862, 2021).
cancer (continued). "In a previous report, MKL1 could also promote cancer cell migration and invasion, which has a similar function as PVT1." (PMID 32156248, 2021). "In addition, copy number variants have been shown to drive co-amplification of PVT1 and MYC in numerous cancers." (PMID 33499210, 2021). "For example, lncRNA PVT1 drives oncogene MYC expression in various types of cancer cells." (PMID 34946814, 2021). "Numerous studies have revealed that PVT1 displays a crucial role to facilitate cancer progression by promoting growth and proliferation, enhancing migration and invasion, suppressing apoptosis, regulating metabolism, maintaining stemness, as well as inducing chemotherapy resistance." (PMID 34760707, 2021). "Co-amplification of adjacent PVT1 and Myc has been found in many human cancers." (PMID 34527584, 2021). "Furthermore, PVT1 promotes breast tumorigenicity by modulating transcription factors that have been demonstrated to have oncogenic roles in cancer." (PMID 33801373, 2021). "We first filtrated ER lncRNAs with continuous status in multiple cancers (EA samples/ES samples > 2 or <0.5 in at least three cancer types) and obtained six EA lncRNAs (PVT1, PSMD5-AS1, FAM83H-AS1, MIR4458HG, HCP5, and GAS5) and three ES lncRNAs (CTD-2201E18.3, HCG11, and AC016747.3)." (PMID 34222227, 2021). "Since increased proliferation is characteristic of cancer cells and has been shown to be regulated by PVT1 exon 9 which is positively correlated with PVT1 exon 4A, we suspect that our score may be predictive of PCa in other races." (PMID 33796469, 2021). "Furthermore, PVT1 can act as a “sponge” for miRNAs and inhibit their activity, thereby affecting cancer proliferation, invasion, and angiogenesis." (PMID 34336125, 2021). "The existence of an aberrant expression of PVT1 in many human cancers has been reported recently." (PMID 32156248, 2021). "PVT1, a lncRNA that often co-amplifies with c-myc and functions as miRNA sponge to upregulate HIF-1α expression, is another example of exosomal transfer between TAMs (tumor associated macrophages) and cancer cells." (PMID 32370770, 2020). "However, PVT1 and circPVT1 potentiate malignant cells, while hampering anti-tumor immune response during cancer progression." (PMID 32228602, 2020). "Furthermore, a much more comprehensive understanding of PVT1 specific interactions with downstream molecular mediators in different cancers is still needed to be able to fully exploit PVT1 for clinical applications." (PMID 32117705, 2020). "Similar to CASC9, PVT1 discovered earlier can promote the occurrence and progression of cancer." (PMID 33585468, 2020). "Targeting PVT1 in cancer is a promising novel approach to cancer treatment." (PMID 32117705, 2020). "By interacting with FOXM, prominent expression of PVT1 enhanced cancer proliferation and invasion." (PMID 32368310, 2020). "However, these recent findings show that there is much more to be learned to be able to fully exploit PVT1 for cancer prognostication and therapy." (PMID 32117705, 2020). "Male mice implanted with RWPE1 cells overexpressing PVT1 exon 9 developed malignant tumors." (PMID 32117705, 2020). "Consequently, we are reporting for the first time that alternatively spliced long non-coding transcripts from PVT1 exons 4A and 4B are significantly overexpressed in a cancer-specific manner in PCa." (PMID 32358016, 2020). "Further studies are needed to explore how PVT1 transcripts are regulated by each other, and which PVT1 transcripts participate in regulatory activities with neighboring genes, as well as the functions of PVT1 transcripts in different types of cancers." (PMID 32117705, 2020). "This negative regulation of miRNAs is seen in many cancers where PVT1 is overexpressed." (PMID 32117705, 2020). "Certainly, identifying the molecular mechanisms of PVT1 could have important implications for therapeutically targeting cancer." (PMID 32117705, 2020). "Meanwhile, c-Myc and PVT1 were co-amplified in many cancers." (PMID 33329315, 2020).
cancer (continued). "The role of PVT1 as a cancer biomarker is progressively becoming established." (PMID 32117705, 2020). "Furthermore, bioinformatic analysis of PVT1 interactions in cancers has aided understanding of the numerous pathways involved in PVT1 contribution to carcinogenesis in a cancer type—specific manner." (PMID 32117705, 2020). "Besides the MYC gene, the 8q24.21 region harbors the PVT1 lncRNA locus, expression of which is consequently elevated in various types of cancer tissues and cell lines as a result of amplifications and translocations." (PMID 33329688, 2020). "PVT1 was the first lncRNA gene identified in human cancer translocations." (PMID 32528946, 2020). "Given the importance of exosomes in tumorigenesis and cancer progression, the present study found that PVT1 could facilitate the secretion of exosomes from PC cells." (PMID 32499447, 2020). "Thus, direct and specific approaches can be used to facilitate targeted anti-PVT1 therapies in patients with cancers." (PMID 32117705, 2020). "Some studies have shown that PVT1 is involved in poor prognosis of cancers." (PMID 32760219, 2020). "Many studies have long established the co-amplification of c-Myc and PVT1 in many cancers." (PMID 32117705, 2020). "In addition, recent reports showed that PVT1 can be as a competing endogenous RNA to sponge miRNAs to governs cancer characters 6, 9, 20,23." (PMID 32201527, 2020). "Aberrations of PVT1 are associated with multiple types of cancer, but the individual exons of PVT1 have not yet been fully characterized." (PMID 32358016, 2020). "But little is known about regulatory mechanism of PVT1 overexpression in cancers." (PMID 32021563, 2020). "Despite the remarkable progress already made in uncovering the role of PVT1 and its mechanisms of action in cancer, there is so much more about PVT1 that remains unknown." (PMID 32117705, 2020). "Both PVT1 and the well-known protein-coding gene MYC are co-located on the 8q24 chromosomal region, known as the gene desert, which contains a large number of risk alleles that are implicated in cancer." (PMID 33076512, 2020). "In addition, human PVT1 is a target of genetic gains and amplifications in a large variety of cancers, including those of the digestive tract." (PMID 32083000, 2020). "It would be worth identifying whether the positive feedback loop between PVT1 and Wnt/β-catenin signaling also functions in the chemo-resistance in other cancer types." (PMID 32727463, 2020). "Novel insight is emerging about PVT1's mechanism of action in different cancers." (PMID 32117705, 2020). "Recent PVT1 was found to promote cell proliferation via regulating the cell cycle in many cancers." (PMID 31320749, 2020). "Therefore, PVT1 regulates glycolysis through competing with different microRNAs in a cancer type-specific manner." (PMID 32174794, 2020). "Both MYC and PVT1 are located on chromosome 8q24, a region amplified in cancer." (PMID 32503290, 2020). "PVT1 can also epigenetically silence miRNAs as part of its regulatory network in some cancers." (PMID 32117705, 2020). "How and when to target PVT1 in cancer remains an important focus." (PMID 32117705, 2020). "Compared to para-carcinoma tissues, the relative expression level of PVT1 was significantly increased about 2.28 times (43 of 70) of BC samples (P<0.001), and the relative expression level of miR-194-5p was significantly decreased about 42.92% (46 of 70) of BC samples (P=0.023)." (PMID 33188158, 2020). "Furthermore, the high and specific expression of PVT1 in human cancer indicates its potential as a biomarker in early clinical diagnosis." (PMID 31309249, 2019). "Moreover, genome-wide screening has identified PVT1 as a regulator of chemotherapy resistance, and PVT1 also plays a vital role in cancer drug resistance." (PMID 31497532, 2019).
cancer (continued). "It is well established that PVT1 overexpression is widespread across multiple cancer types, making the lncRNA PVT1 of particular interest in the search for processes and pathways involved in cancer progression." (PMID 31249809, 2019). "Therefore, through this positive feedback mechanism, PVT1 and c-Myc in cancer cells can remain at a high level, which results in the synergistic promotion of tumorigenesis by PVT1 and c-Myc." (PMID 31309249, 2019). "PVT1 encodes a long non-coding RNA; it is usually co-amplified with c-myc and is required for the expression of MYC and tumorigenesis of a wide variety of cancers." (PMID 31041889, 2019). "In recent years, a growing number of studies have shown that PVT1 upregulated in several cancers." (PMID 30083911, 2019). "It is worth further investigating whether CircPVT1 has similar mechanisms to PVT1 in cancer cells, whether CircPVT1 interacts with MYC, and which molecules CircPVT1 can regulate to participate in the downstream signaling pathway of c-Myc." (PMID 31309249, 2019). "First, PVT1 played a key role in cancers by interacting with miRNAs." (PMID 30083911, 2019). "Pvt1 has been extensively studied in cancer where it is known to regulate the expression of c-Myc." (PMID 30649422, 2019). "In addition, PVT1 itself can also be spliced into 6 different miRNAs, namely miR-1204, miR-1205, miR-1206, miR-1207-5p, miR-1207-3p, and miR-1208, with either cancer-inducing or cancer-inhibiting function." (PMID 31380270, 2019). "First, genomic alteration of PVT1 was analyzed using the TCGA dataset across multiple cancer types; we found that ESCA was the second-ranking cancer type with high PVT1 alterations with 20% PVT1 amplification and around 75% of ESCA cases contained both amplification and duplications (> 3 N)." (PMID 31601234, 2019). "Finally, PVT1 also affected cell cycle progression, such as promoted cell proliferation, migration and invasion and inhibited cell apoptosis in various cancers." (PMID 30083911, 2019). "The key findings are that through E2F1, FOXM1 and PVT1 regulatory axis and possible interactions with different coding genes, PVT1 may be playing a prominent role in pan-cancer development and progression." (PMID 30809433, 2019). "PVT1 can also serve as a potential predictor of cancer progression and patient prognosis." (PMID 31309249, 2019). "In addition, PVT1 interacts with miRNAs and regulates gene transcription and protein expression, thereby exerting effects on cancer cells." (PMID 31497532, 2019). "Interestingly, when siRNA was used to knock down PVT1, low levels of c-Myc were found without significant changes in MYC mRNA levels, which indicates that c-Myc levels are closely related to PVT1 in high-copy 8q24 proliferating cancer cells." (PMID 31309249, 2019). "PVT1 is one of the LncRNAs, which is highly expressed in some type of cancers and promotes cancer cell proliferation and stem cell-like property, and knockdown of PVT1 could weaken the resistance to doxorubicin and cisplatin." (PMID 31028131, 2019). "Recently, several studies have suggested that PVT1 and Myc may exert synergistic effects in cancer initiation." (PMID 31497532, 2019). "PVT1 is an important oncogenic lncRNA highly expressed in cancer cells." (PMID 31380270, 2019). "In addition, PVT1 itself can be spliced and processed into several miRNAs such as miR-1204 and miR-1207, which can also regulate the development of cancer." (PMID 31380270, 2019). "Notably, implantation into mice of a non-tumorigenic prostate epithelial cell line stably overexpressing PVT1 exon 9 resulted in the formation of malignant tumors." (PMID 31766781, 2019). "PVT1 is the first long non-coding RNA (lncRNA) identified in human cancer." (PMID 31601234, 2019). "The further comprehensive mechanism between PVT1 and cancers was reported in continuance." (PMID 30083911, 2019). "Our review should aid in the understanding of PVT1 and PVT1-based therapy in cancer." (PMID 31497532, 2019).